CTLA4 (cytotoxic T-lymphocyte associated protein 4)
Diseases named in the same sentence as CTLA4 in open-access papers (continued):
Sharing a sentence is not in itself a finding about the gene and the disease.
cervical carcinoma (90 papers, 2011 to 2026). A carcinoma arising from either the exocervical squamous epithelium or the endocervical glandular epithelium. "The CTLA4 genetic variants rs5742909 (−318 C>T), rs231775 (+49 A>G), and rs3087243 (+6230 G>A) have already been associated with the development of cervical cancer in different populations, but the results are contradictory." (PMID 40284896, 2025). "The polymorphisms of the fundamental immunosuppressive cytokine, cytotoxic T-lymphocyte antigen-4 (CTLA4, CD152), which terminates the T-cell response and prohibits T-cell activation, are associated with the risk of breast and cervical cancers." (PMID 36248961, 2022). "It has been shown recently that single nucleotide polymorphisms in the promoter region of the CTLA‐4 gene correlate with higher susceptibility to various types of malignancies including cervical cancer." (PMID 33205441, 2021). "CTLA-4 was identified as a prognostic marker for cervical cancer, with a higher susceptibility in Asian populations, and studies have shown that low T-reg frequencies were associated with longer OS." (PMID 34123823, 2021). "Blocking antibodies against cytotoxic T-lymphocyte-associated protein 4 (CTLA-4) and PD-1/PD-L1 immune checkpoints have shown durable clinical responses in a variety of cancers, including cervical cancer." (PMID 34778035, 2021). "Anti-cytotoxic T lymphocyte-associated antigen 4 (CTLA-4) is another target for therapy being studied in a variety of malignancies, including cervical cancer." (PMID 34898560, 2021). "In the Chinese population, the CTLA-4 + 49a allele is associated with increased risk of lung, breast and cervical cancers." (PMID 33226370, 2020). "Recently, we reported our results of cervical cancer and found that the genotype AA of CTLA4 G49A was associated with a 1.66-fold (95% CI=1.13-2.44) increased cervical cancer risk." (PMID 23554684, 2011). "Additionally, ipilimumab, a cytotoxic T-lymphocyte-associated antigen 4 (CTLA-4) inhibitor, as well as nivolumab, another PD-1 receptor antagonist, have shown promise in recurrent, persistent, or metastatic ovarian and cervical cancer." (PMID 37444636, 2023). "However, a plus point is that we collected sociodemographic data as well as data on the sexual and reproductive behavior of the participants, which allowed for an analysis of the possible confounding factors in the study of CTLA4 genetic variants potentially associated with cervical cancer." (PMID 40284896, 2025). "Speaking of prognosis, studies have established prognostic models in cervical cancer using m6A/m5C/m1A-related genes to predict survival time and its correlation with immune cell infiltration, and found associations with sensitivity to anti-CTLA-4 immunotherapy drugs." (PMID 39726589, 2024). "Although PD-1 inhibitors are currently first-line agents for cervical cancer immunotherapy, CTLA-4 inhibitors remain under clinical investigation." (PMID 40808954, 2025). "Cadonilimab is a bispecific antibody against PD-1 and CTLA4, which has completed two Phase II studies in patients with metastatic or recurrent cervical cancer (NCT04380805, NCT04868708)." (PMID 40417700, 2025). "CTLA-4 represents another critical immune checkpoint pathway gaining attention in cervical cancer therapy." (PMID 40808954, 2025). "Several studies found CTLA4 expression in a variety of tumors such as breast, lung, and cervical cancer, and in hematological malignancies and ovarian, uterine, and cervical cancer cell lines." (PMID 39592485, 2025). "This study also identified cases of immune-mediated colitis in cervical cancer patients following pembrolizumab treatment, with a lower incidence compared to CTLA-4 inhibitors." (PMID 40264768, 2025). "Despite being in the exploratory phase, CTLA-4 blockade holds significant promise as a future strategy for cervical cancer immunotherapy." (PMID 40808954, 2025).
cervical carcinoma (continued). "Preliminary results from the ongoing phase I/II trial of balstilimab (anti-PD-1) as monotherapy or in combination with zalifrelimab (anti-CTLA-4) in patients with metastatic or locally advanced cervical cancer were also presented." (PMID 38541669, 2024). "The Cancer Imaging Archive data analysis revealed that the impact of anti-PD1 and CTLA4 therapy is more pronounced in cervical cancer patients exhibiting elevated IDO1 expression." (PMID 39312339, 2024). "Immune checkpoint inhibitors (e.g., PD-1/PD-L1, CTLA-4) have shown potential therapeutic effects in cervical cancer." (PMID 38206304, 2024). "The use of immune checkpoint inhibition therapy, which targets immune checkpoints, CTLA-4 and PD-1/PD-L1, has shown promise as an alternate standard of care for patients suffering from advanced-stage cervical cancer." (PMID 38816670, 2024). "Efficacy and safety of QL1706, a novel dual immune checkpoint blockade containing a mixture of anti-PD1 IgG4 and anti-CTLA4 IgG1 antibodies, for advanced cervical cancer: Cohort data from a phase 1b trial." (PMID 36817443, 2023). "In June 2022 Cadonilimab (a bispecific antibody targeting PD-1 and CTLA-4) was approved in China to treat patients with relapsed or metastatic cervical cancer." (PMID 36817443, 2023). "At the same time, the dual specific antibody of PD-1/CTLA-4 was also used in clinical trials of cervical cancer, and the results showed better than anti-PD-1 monotherapy." (PMID 37559727, 2023). "The first-in-class anti-PD-1/CTLA-4 bispecific to be recently approved for the treatment of advanced cervical cancer has been Cadonilimab, which is a quadrivalent bispecific with similar format to MEDI8500." (PMID 36936963, 2023). "It was found that MLK4 mRNA expression was significantly positively correlated with immune checkpoint PD-L1, CTLA4, LAG3etc, which were related to the regulation of T cells in cervical cancer." (PMID 37594950, 2023). "Cadonilimab (AK104) is a PD-1/CTLA-4 bispecific antibody that had been approved in China to treat patients with relapsed or metastatic cervical cancer who have progressed on or after platinum-based chemotherapy." (PMID 36817443, 2023). "Nivolumab is often combined with anti-CTLA-4 antibody ipilimumab, not only for recurrent/metastatic cervical cancer in the classical CheckMate 358 (NCT02488759) but also for locally advanced cervical cancer when combined with chemoradiotherapy." (PMID 36817443, 2023). "At the same time, some dual ICIs, such as AK-104 (anti-PD-1/CTLA-4 bispecific antibody), have been registered for clinical research on cervical cancer (NCT04380805; NCT05063916; NCT05235516; NCT04982237; NCT04868708)." (PMID 36387196, 2022). "Currently, ICB therapies, especially those using PD‐L1/PD‐1 and CTLA4 inhibitors, are among the novel methods for treating metastatic cervical cancers." (PMID 35986392, 2022). "Recently, immunotherapy agents have been suggested for cervical carcinomas, such as anti-CTLA-4, anti-PD-1, anti-PD-L1, anti-VEGF, and anti-EGFR agents." (PMID 36276117, 2022). "To date, there has been no prospective study on the use of combined anti-PD-1 and anti-CTLA-4 therapy at the time of progression on anti-PD-1 therapy in patients with MSI-H tumors or advanced cervical cancer." (PMID 35640145, 2022). "The most studied immune checkpoints in cervical cancer include programmed death 1/programmed death ligand-1 (PD-1/PD-L1) and cytotoxic T lymphocyte antigen (CTLA-4)." (PMID 36387196, 2022). "Activation of glycolysis induces PD-L1 expression on these cells and subsequently attenuates cytotoxic T lymphocyte responses in tumor tissue, dendritic cells induce peripheral CD8+ T cell tolerance through PD-1 and CTLA-4, and in cervical cancer." (PMID 35799142, 2022).
cervical carcinoma (continued). "The C550 study is the largest reported phase II study that evaluated the antitumor activity of the combination of balstilimab (an anti-PD-1 antibody) with zalifrelimab (an anti-CTLA-4 antibody) as a second-line therapy for advanced cervical cancer." (PMID 36387196, 2022). "In a phase I/II trial investigating the effects of ipilimumab (anti-CTLA-4) monotherapy in patients with metastatic or recurrent cervical cancer (n = 42), there was an overall response rate of only 2.9% (1/42; 1 PR)." (PMID 35207374, 2022). "The results of the study showed that the anti-CTLA-4 monoclonal antibody ipilimumab had some efficacy for metastatic or recurrent cervical cancer." (PMID 35371317, 2022). "An anti-programmed cell death 1 (PD-1) mAb and anti-cytotoxic T lymphocyte-associated antigen 4 (CTLA-4) mAb are treatments studied in a variety of malignant tumours, including cervical cancer." (PMID 35729552, 2022). "Ipilimumab, the CTLA‐4 inhibitor, characterized the safety and manageable toxicities in cervical cancers with below‐par performance, the same as nivolumab targeting PD‐1." (PMID 33694292, 2021). "An active phase I study was designed to evaluate the safety and tolerance of tremelimumab, anti‐CTLA‐4 antibody and durvalumab in various advanced solid tumours including cervical cancer (NCT01975831)." (PMID 33205441, 2021). "Ipilimumab, a fully human anti‐CTLA‐4 monoclonal antibody, is being tested in a phase II study to assess its efficacy in patients with recurrent or metastatic cervical cancer (NCT01693783)." (PMID 33205441, 2021). "This study did show evidence of PD-L1 changes with CTLA-4 inhibitor monotherapy in patients with metastatic or recurrent cervical cancer post CRT." (PMID 34123823, 2021). "CTLA-4–Ig-transfected J558L murine myeloma,T-cells, isotype control, C33a cervical cancer cell line and surface staining of resting T-cells." (PMID 33384695, 2020). "In terms of treatment combinations, tremelimumab (a fully human mAb against CTLA-4), Vigil vaccine for cervical cancer, bevacizumab, and chemotherapy were paired with PD-1/PD-L1 inhibitors throughout these studies." (PMID 30774597, 2019). "The expression of markers of the immune system such as CD95, MICA/B, CD39, CD73, NKp30, NKp46, CD44, CD24, NKG2A, and CTLA-4 was analysed by flow cytometry on cervical cancer cells INBL (HPV 18, stage IVB), HeLa (HPV 18), CaSki (HPV 16), and C33A (HPV-)." (PMID 31198791, 2019). "The clinical benefits of blocking the CTLA-4 immune inhibitory pathway is also under clinical evaluation in cervical cancer and HNSCC patients." (PMID 29179871, 2017). "In brief, we have shown that allele T of the CTLA4 genetic variant rs5742909 (−318 C>T) and the TAG haplotype are associated with HPV infection, the development of cervical intraepithelial lesions, and cervical cancer in a cohort of the Brazilian population." (PMID 40284896, 2025). "In cervical cancer, PD-1/CTLA-4 BSABs may confer a longer survival period than PD-L1/TGF-β BSABs (mOS, 17.5 vs. 13.4 months)." (PMID 38627681, 2024). "Therefore, evidence supporting the involvement of CD44 in promoting enhanced immune evasion potential through the upregulated expression of both PD-L1 and CTLA-4 in cervical cancer cells is evident." (PMID 38816670, 2024). "Clinical trials have demonstrated that Zalifrelimab (anti-CTLA-4) and Balstilimab (anti-PD-1) possess acceptable safety profiles and induce sustained responses, highlighting their potential as effective therapies for advanced cervical cancer." (PMID 39840054, 2024). "Interestingly, they observed both the CaSki and HeLa cervical cancer cell lines with corresponding high levels of CD44 in conjunction with the high CTLA-4 levels." (PMID 38816670, 2024). "Besides the widely researched target such as CTLA-4 and PD-1/PD-L1, some novel co-inhibitory immune checkpoints and their antibodies have also been explored in cervical cancer, such as TIGIT, LAG-3, and TIM-3." (PMID 36817443, 2023).
cervical carcinoma (continued). "In addition, the CTLA-4 49A/G SNP was related to infection-related hepatocellular and cervical carcinomas." (PMID 37107632, 2023). "It was reported that a prognostic signature consisting of immune-related long non-coding RNAs, such as CTLA-4, PDCD1, and so on, correspondingly predicted risk of cervical cancer and responded to cervical cancer patients’ immunotherapy of mitomycin C and chemotherapeutics of axitinib and docetaxel." (PMID 36536343, 2022). "Moreover, dual PD-1 and CTLA-4 blockage combination displayed durable clinical activity and favorable tolerability as the second-line therapeutic regimen for advanced cervical cancer." (PMID 36313466, 2022). "Identification of KIN-related prognostic genes in cervical cancer revealed that a total of 5 genes (FZR1, IMPDH1, GPKOW, XPA, and DDX39A) were constructed for this risk score, and the results showed that CTLA4 expressions were negatively correlated with the risk score." (PMID 35909901, 2022). "This would suggest exploration of CTLA-4 as a meaningful target in cervical cancer." (PMID 34123823, 2021). "Considering favorable efficacy in immune checkpoint inhibitors (especially PD‐1/PD‐L1 inhibitors) achieved in treating cervical cancer, our study also assessed the expression status of CTLA4, PD‐1, and PD‐L1 in cervical cancer patients grouped by different expression of HOXA1, HOXA10, and HOXA11." (PMID 34606634, 2021). "As seen when analyzing the Treg frequency in tumors of cervical cancer, patients with high Treg frequency have significantly shorter OS than patients with low Treg frequency, indicating that an anti-CTLA-4 antibody could be a treatment target." (PMID 31533297, 2019). "In cervical cancer, 7 genes were identified for CTLA4, 3 genes for CD274." (PMID 27683114, 2016). "The CTLA4 genetic variants rs5742909 (−318 C>T), rs231775 (+49 A>G), and rs3087243 (+6230 G>A) have not been previously associated with the development of cervical cancer in the Brazilian population, and the results of studies in other populations are contradictory, as shown." (PMID 40284896, 2025). "Additionally, CTLA-4 blockade with ipilimumab is being explored in cervical cancer treatment." (PMID 38541669, 2024). "However, several studies have investigated the relationship between the CTLA4 G49A variation and cervical cancer risk but have not found any significant associations." (PMID 23554684, 2011). "However, a study examining haplotypes composed of the CTLA4 genetic variants −1722 (C>T), −1661 (A>G), −318 (C>T), and +49 (A>G) found that the presence of the TGCG haplotype may be associated with an increased risk of cervical cancer." (PMID 40284896, 2025). "Inhibits PD-1/PD-L1, CTLA-4 pathways, restoring T-cell activity to recognize and destroy HPV-transformed cervical cancer cells." (PMID 41403730, 2025). "In cervical cancer patients, we found CSCC cohorts obtained higher TMB score, MSI score and common inhibitory checkpoints expression (e.g., PDCD1, CD274, BTLA, CTLA4, TIGIT, etc.), accompanied by more abundant immunocytes infiltration." (PMID 38206304, 2024). "In a clinical trial involving 155 women with advanced cervical cancer, the objective response rate (ORR) of dual PD-1/ CTLA-4 blockade therapy was only 25.6%." (PMID 35879796, 2022). "Immunotherapy consisting of anti-CTLA4 and anti-PD1 agents has been reported to be effective in the treatment of oropharyngeal cancer and cervical cancer." (PMID 36536343, 2022). "Concordantly, there are several studies by the Agenus corporation currently examining the role of CTLA-4 inhibitor, or AGEN1884, in cervical cancer." (PMID 34123823, 2021). "DUET-4 trial of the bispecific antibody targeting CTLA-4 and LAG-3 alone or in combination with pembrolizumab is an early phase study of patients with advanced malignancies including cervical cancer (NCT03849469)." (PMID 34640541, 2021).
cervical carcinoma (continued). "Anti-CTLA-4 monoclonal antibodies or CTLA-4 vaccines constructions were developed in order to prevent CTLA-4 activities and it has been tested or are in ongoing trials for treatment of cervical cancer and HNSCC." (PMID 29976244, 2018). "As in cervical cancer as in HNSCC, CTLA-4 was found to be highly expressed, being frequently associated with poor prognosis." (PMID 29976244, 2018). "Accumulation of CTLA-4+ Treg cells in the HPV-positive HNSCC tumor microenvironment and in the peripheral blood of advanced cervical cancer patients, suggests a repressive role for CTLA-4 during HPV infection." (PMID 29179871, 2017). "Moreover, immunotherapy has emerged as a key treatment modality in cervical cancer by inhibiting immune checkpoint inhibitors (PD1, PD-L1, and CTLA4)." (PMID 41749817, 2026). "In addition, high expression of immune checkpoints, such as Cytotoxic T lymphocyte antigen 4 (CTLA4) and programmed cell death 1/programmed cell death-ligand 1 (PD1/PD-L1), has been demonstrated in intraepithelial lesions and cervical cancer." (PMID 39124724, 2024). "On the other hand, monotherapy with ipilimumab and CTLA-4 inhibition was not approved in cervical cancer patients due to a lack of targeted treatment." (PMID 36276117, 2022). "In cervical cancer, FANCE expression was positively correlated with PDL1 and CTLA4." (PMID 36685883, 2022). "Other combinations under investigations include AGEN1884 (anti-CTLA-4) and AGEN2034 (anti-PD-1), with safety data reported from a phase I/I trial including patients with refractory solid organ malignancies (expansion in patients with cervical cancer)." (PMID 34640541, 2021). "This study predicts that anti-CTLA-4 therapy may serve as an immunotherapeutic agent for managing cervical cancer and that the expression of CUX1, SLC2A1, and CA2 genes validated by clinical samples may serve as important targets for treatment modalities in cervical cancer." (PMID 37042849, 2023). "PD-1/CTLA-4 and PD-L1/TGF-β BSABs demonstrate comparable efficacy (ORR, 33% and 28.2%, respectively) in patients with advanced cervical cancer who have not received immunosuppressive therapy." (PMID 38627681, 2024).